COPG2 (coat protein complex I subunit gamma 2)
Description:
The coatomer is a cytosolic protein complex that binds to dilysine motifs and reversibly associates with Golgi non-clathrin-coated vesicles, which further mediate biosynthetic protein transport from the ER, via the Golgi up to the trans Golgi network. Coatomer complex is required for budding from Golgi membranes, and is essential for the retrograde Golgi-to-ER transport of dilysine-tagged proteins. In mammals, the coatomer can only be recruited by membranes associated to ADP-ribosylation factors (ARFs), which are small GTP-binding proteins; the complex also influences the Golgi structural integrity, as well as the processing, activity, and endocytic recycling of LDL receptors (By similarity).
Synonyms: Gamma-2-COP; 2-COP
Tractability: Antibody: UniProt places it where antibodies can reach, with medium confidence. PROTAC: ubiquitination databases record sites on it; its protein half-life has been measured.
Gene: Protein-coding gene on chromosome 7 (130,506,238 to 130,668,748, reverse strand). Ensembl gene ENSG00000158623.
Subcellular location: Cytoplasm, cytosol; Golgi apparatus membrane; Cytoplasmic vesicle, COPI-coated vesicle membrane
Pathways (Reactome):
Vesicle-mediated transport: COPI-dependent Golgi-to-ER retrograde traffic; COPI-mediated anterograde transport
Gene Ontology:
Molecular function: structural molecule activity
Biological process: intra-Golgi vesicle-mediated transport; endoplasmic reticulum to Golgi vesicle-mediated transport; organelle transport along microtubule; protein secretion; retrograde vesicle-mediated transport, Golgi to endoplasmic reticulum; intracellular protein transport; vesicle-mediated transport
Cellular component: COPI vesicle coat; cytosol; endoplasmic reticulum; endoplasmic reticulum membrane; endoplasmic reticulum-Golgi intermediate compartment; Golgi membrane; transport vesicle; bounding membrane of organelle; COPI-coated vesicle; COPI-coated vesicle membrane; Golgi apparatus; growth cone; membrane coat
Genetic constraint (gnomAD): Loss-of-function variants: 8 observed, 12.75 expected, observed/expected ratio (o/e) 0.63, 90% interval 0.37 to 1.13. The upper end of that interval is the gene's LOEUF score, 1.13, which puts it in group 4 of 6, group 1 being the genes least tolerant of losing a copy. Missense variants: 112 observed, 115.2 expected, observed/expected ratio (o/e) 0.97, 90% interval 0.83 to 1.14. Synonymous variants: 43 observed, 41.78 expected, observed/expected ratio (o/e) 1.03, 90% interval 0.81 to 1.33.
Homologues: Orthologues: chimpanzee COPG2 (100% identical), macaque COPG2 (98% identical), mouse Copg2 (98% identical), dog COPG2 (97% identical), rat Copg2 (97% identical), pig COPG2 (95% identical), tropical clawed frog copg2 (90% identical), zebrafish copg2 (89% identical), rabbit COPG2 (75% identical), Drosophila melanogaster gammaCOP (60% identical), Caenorhabditis elegans copg-1 (56% identical). Paralogues in human: COPG1 (81% identical).
Diseases named in the same sentence as COPG2 in open-access papers:
COPG2 is named in the same sentence as 11 diseases in open-access papers, as found by Europe PMC text mining. Sharing a sentence is not in itself a finding about the gene and the disease. The quoted sentences say what the papers report.
breast carcinoma (2 papers, 2010 to 2012). "We quantitatively analyzed the expression profiles of 160 proteins in MDA-MB-231 breast cancer cells 48 or 72 hours post-infection with non-targeting control siRNA or siRNA targeting COPB2 or COPG2." (PMID 22745748, 2012).
embryonal carcinoma (1 paper, 2020). A non-seminomatous malignant germ cell tumor characterized by the presence of large germ cells with abundant cytoplasm resembling epithelial cells, geographic necrosis, high mitotic activity, and pseudoglandular and pseudopapillary structures formation. "To examine whether a differential expression of Copg1 and Copg2 is also observed in another neuronal differentiation system we then analyzed mRNA and protein levels of the two γ-COP paralogs in P19 embryonal carcinoma cells." (PMID 32665377, 2020).
cancer (4 papers, 2012 to 2024). A tumor composed of atypical neoplastic, often pleomorphic cells that invade other tissues. "Consistent with the data obtained in cancer cells exogenously overexpressing GFP-LC3 and with the exception of COPG2, reducing the expression of the coatomer subunits led to an accumulation of endogenous LC3-II in MDA-MB-231 cells." (PMID 22745748, 2012).
COPG2 also shares sentences with these, for which no sentence is quoted: infection (2 papers); amyloid (1); autism (1); cystic fibrosis (1); Obesity (1); prostate carcinoma (1); Silver Russel syndrome (1); tuberculosis (1).